CILP (cartilage intermediate layer protein)
Description:
Probably plays a role in cartilage scaffolding. May act by antagonizing TGF-beta1 (TGFB1) and IGF1 functions. Has the ability to suppress IGF1-induced proliferation and sulfated proteoglycan synthesis, and inhibits ligand-induced IGF1R autophosphorylation. May inhibit TGFB1-mediated induction of cartilage matrix genes via its interaction with TGFB1. Overexpression may lead to impair chondrocyte growth and matrix repair and indirectly promote inorganic pyrophosphate (PPi) supersaturation in aging and osteoarthritis cartilage.
Synonyms: CILP-1; HsT18872; CILP1
Tractability: Antibody: UniProt places it where antibodies can reach, with high confidence; its Gene Ontology location is reachable by antibodies, with high confidence; UniProt predicts a signal peptide or a membrane-spanning region. PROTAC: ubiquitination databases record sites on it.
Gene: Protein-coding gene on chromosome 15 (65,194,760 to 65,211,478, reverse strand). Ensembl gene ENSG00000138615.
Subcellular location: Secreted, extracellular space, extracellular matrix
Pathways (Reactome):
Signal Transduction: Signaling by Type 1 Insulin-like Growth Factor 1 Receptor (IGF1R)
Gene Ontology:
Molecular function: alkaline phosphatase activity; dinucleotide phosphatase activity; extracellular matrix structural constituent
Biological process: negative regulation of gene expression; negative regulation of insulin-like growth factor receptor signaling pathway; negative regulation of SMAD protein signal transduction; negative regulation of transforming growth factor beta receptor signaling pathway
Cellular component: extracellular exosome; extracellular matrix; extracellular region; non-collagenous component of interstitial matrix
Genetic constraint (gnomAD): Loss-of-function variants: 73 observed, 82.35 expected, observed/expected ratio (o/e) 0.89, 90% interval 0.73 to 1.08. The upper end of that interval is the gene's LOEUF score, 1.08, which puts it in group 4 of 6, group 1 being the genes least tolerant of losing a copy. Missense variants: 1,455 observed, 1,570.5 expected, observed/expected ratio (o/e) 0.93, 90% interval 0.89 to 0.97. Synonymous variants: 517 observed, 599.25 expected, observed/expected ratio (o/e) 0.86, 90% interval 0.8 to 0.93.
Homologues: Orthologues: chimpanzee CILP (99% identical), macaque CILP (97% identical), dog CILP (91% identical), pig CILP (91% identical), mouse Cilp (90% identical), rat Cilp (89% identical), rabbit CILP (89% identical), guinea pig CILP (87% identical), tropical clawed frog cilp (65% identical), zebrafish cilp (62% identical). Paralogues in human: CILP2 (48% identical).
Diseases named in the same sentence as CILP in open-access papers:
CILP is named in the same sentence as 49 diseases in open-access papers, as found by Europe PMC text mining. Sharing a sentence is not in itself a finding about the gene and the disease. The quoted sentences say what the papers report.
osteoarthritis (13 papers, 2014 to 2025). A noninflammatory degenerative joint disease occurring chiefly in older persons, characterized by degeneration of the articular cartilage, hypertrophy of bone at the margins and changes in the synovial membrane. "CILP, an extracellular matrix protein abundant in cartilaginous tissues,is implicated in common musculoskeletal disorders, including osteoarthritis and lumbardisc disease." (PMID 29489999, 2018). "Meanwhile, CILP‐1 has been detected up‐regulated significantly along with osteoarthritis and revealed to be an important contributor to the initialisation and development of osteoarthritis, while the underlying mechanism remains to be illustrated." (PMID 40122778, 2025). "The cartilage intermediate layer protein (CILP) is one of many glycoproteins that have been in the focus of research of joint diseases, such as osteoarthritis (OA)." (PMID 39311368, 2024). "Since CILP-2 rather than CILP-1 has been suggested to be related to the progression of osteoarthritis, some diagnostic value has been attributed to it." (PMID 39506696, 2024). "Similarly, cartilage intermediate layer protein (CILP) is another ECM scaffolding protein, and its increased cleavage is associated with osteoarthritis and disc degeneration." (PMID 29215065, 2017). "Of note, CILP has been primarily described as a joint-based protein and been implicated in osteoarthritis and spinal disc disease, and antibody to non-citrullinated CILP as well as T cell reactivity to cit-CILP have been demonstrated in patients with classified RA15,35." (PMID 37993439, 2023).
disc degeneration (7 papers, 2017 to 2024). "The CILP rs2073711 TT genotype was associated with disc degeneration (DD) in a Finnish study." (PMID 29233086, 2017). "The molecular mechanism by which CILP promotes disc degeneration is significantly related to its inhibitory function of the TGF‐β/Smad3 pathway, which is critical in maintaining the natural metabolism of the NP matrix." (PMID 38023721, 2023). "The inherited genes associated with disc degeneration include those for collagen type I and IX (COL1A1, and COL9A2 and COL9A3, respectively), aggrecan, vitamin D receptor, matrix mettalopeptidase-3 (MMP3), and cartilage intermediate layer protein (CILP)." (PMID 30646556, 2019).
intervertebral disc degeneration (6 papers, 2021 to 2025). "Intervertebral Disc Degeneration (IDD) is a multifactorial result contributing to Low Back Pain (LBP) while Cartilage Intermediate Layer Protein‐1 (CILP‐1) is gradually up‐regulated along with IDD." (PMID 40122778, 2025). "Intervertebral disk degeneration (IDD) is caused by nucleus pulposus (NP) degeneration and extracellular matrix (ECM) remodeling and cartilage intermediate layer protein (CILP) expression has been confirmed to be increased in IDD." (PMID 34233701, 2021).
lumbar disc disease (5 papers, 2010 to 2025). "Furthermore, a functional SNP in Cartilage Intermediate Layer Protein (CLIP) is associated with lumbar disc disease." (PMID 20214815, 2010). "Furthermore, the gene CILP codes for a protein involved in cartilage structure, that is expressed abundantly in intervertebral discs and a SNP in this gene was shown to be a modulator of susceptibility to lumbar disc disease." (PMID 24367280, 2013).
pulmonary hypertension (5 papers, 2023 to 2025). Increased pressure within the pulmonary circulation due to lung or heart disorder. "Emerging biomarkers for RV maladaptation in pulmonary hypertension are long non-coding RNA H19, SPARC-like protein 1 (SPARCL1), and cartilage intermediate layer protein 1 (CILP1)." (PMID 39064541, 2024). "However, CILP-1 has also been related to pulmonary hypertension and cardiac fibrosis, suggesting it is not specific to articular cartilage 27–29." (PMID 38066013, 2023).
breast carcinoma (3 papers, 2013 to 2024). "The genes are associated with laryngeal cancer (MEOX2), cervical cancer (FGF7), oral cancer (DPT), breast cancer (CILP) or ovarian cancer (TMEM119) and LAMP3-positive dendritic cells are generally associated with cancer." (PMID 38671536, 2024). "The aim of our study was to explore the effect of the cartilage intermediate layer protein (CILP) on breast cancer brain metastases (BCBM)." (PMID 35711946, 2022).
heart failure (3 papers, 2023 to 2024). Inability of the heart to pump blood at an adequate rate to meet tissue metabolic requirements. "Upregulation of CILP-1 occurs upon cardiac injury in fibrotic regions, and there is a decrease in serum of patients with heart failure." (PMID 37576554, 2023). "This study examines CILP-1 as a potential biomarker for RVD and prognosis in heart failure with reduced ejection fraction (HFrEF) patients on guideline-directed medical therapy." (PMID 38132152, 2023). "In addition, as shown in the volcano plot, the levels of active fibroblast markers (POSTN, THBS4, CILP, and FN1) were increased in the heart failure group." (PMID 39198543, 2024). "In addition, we found that active fibroblast markers (POSTN, THBS4, CILP, and FN1) were significantly elevated in the heart failure group." (PMID 39198543, 2024).
Myocardial fibrosis (3 papers, 2023 to 2025). "Cartilage intermediate layer protein 1 (CILP1), an extracellular matrix-derived protein, acts as a transforming growth factor-β antagonist and is involved in myocardial fibrosis." (PMID 36882760, 2023). "Analysis of three single-cell transcriptomics data revealed that CILP1 (cartilage intermediate layer protein 1) was specifically secreted from fibroblasts to promote myocardial fibrosis via the mTORC1 (mechanistic target of rapamycin complex 1) pathway in heart." (PMID 37920179, 2023).
dilated cardiomyopathy (2 papers, 2023 to 2025). Cardiomyopathy which is characterized by dilation and contractile dysfunction of the left and right ventricles. "Higher myocardial CILP-1 levels were also reported in patients with hypertrophic cardiomyopathy, and higher circulating CILP-1 levels were found in patients with dilated cardiomyopathy compared with controls." (PMID 38132152, 2023). "In these manuscripts, patients with PH had higher CILP-1 levels compared with patients with dilated cardiomyopathy and preserved RV function, while maladaptive RVD in PH was characterized by even higher levels." (PMID 38132152, 2023).
influenza (2 papers, 2020 to 2024). An acute viral infection of the respiratory tract, occurring in isolated cases, in epidemics, or in pandemics; it is caused by serologically different strains of viruses (influenzaviruses) designated A, B, and C, has a 3-day incubation period, and usually lasts for 3 to 10 days. "CXCR5 expressing cells on the other hand were mainly detected among CILP/fibrinogen- and influenza-specific T cells and rather less among cells recognizing α-enolase." (PMID 32423478, 2020). "We found little expression of both CD25 and CCR6 on the influenza-specific as well as the general CD4 population, while such phenotypes were detected in α-enolase- and CILP/fibrinogen-specific T cells." (PMID 32423478, 2020). "No decrease in frequency was seen over time for influenza, cit-fibrinogen-β/vimentin or cit-α-enolase/CILP-specific cells in any of the groups." (PMID 39557489, 2024).
thyroid cancer (2 papers, 2018 to 2021). "All the ten thyroid cancer cell lines tested showed loss of CILP expression." (PMID 29321030, 2018). "Notably, all thyroid cancer cell lines had loss of CILP expression." (PMID 29321030, 2018). "Gene expression values (normalized read counts) of C1QL1 (a), LCN2 (b), CRABP1 (c) and CILP (d) in differentiated thyroid cancer (DTC) and normal thyroid (NT) tissues available in The Cancer Genome Atlas (TCGA)." (PMID 29321030, 2018). "A regression model was performed with C1QL1, LCN2, CRABP1 and CILP expression values for thyroid cancer prognostic factors: age of patients (> 45 years), tumour size (> 4 cm), and presence of extrathyroidal extension of the tumour." (PMID 29321030, 2018). "CILP expression levels were successfully measured by qPCR in 88 DTC (14 FTC, 20 FVPTC and 54 PTC), 10 thyroid cancer cell lines, 17 FTA, and twelve matched thyroid normal tissues." (PMID 29321030, 2018). "Finally, to find prognostic makers of THCA, we performed survival correlation analysis on all genes in samples of thyroid cancer patients, and finally determined five hub genes based on the log-rank value: CD47, CILP, DERA, KLHL33, PSMB8." (PMID 34376710, 2021).
triple-negative breast carcinoma (2 papers, 2022). An invasive breast carcinoma which is negative for expression of estrogen receptor (ER), progesterone receptor (PR), and human epidermal growth factor receptor 2 (HER2). "UALCAN analysis showed that CILP expression was downregulated in HER2-positive (HER2+) and triple-negative breast cancer (TNBC), which are more prone to BM." (PMID 35711946, 2022).
ankylosing spondylitis (1 paper, 2023). An autoimmune chronic inflammatory disorder characterized by inflammation in the vertebral joints of the spine and sacroiliac joints. "Moreover, studies investigating the role of CILP-1 in other joint-related diseases such as ankylosing spondylitis (AS) are needed to further elucidate its function and implication in cartilage structure and pathology." (PMID 38066013, 2023).
Arthralgia (1 paper, 2020). "The remaining three arthralgia patients had one of the three citrullinated specificities; two displayed vimentin-reactive and one CILP/fibrinogen-specific T cells." (PMID 32423478, 2020).
atrial fibrillation (1 paper, 2023). A disorder characterized by an electrocardiographic finding of a supraventricular arrhythmia characterized by the replacement of consistent P waves by rapid oscillations or fibrillatory waves that vary in size, shape and timing and are accompanied by an irregular ventricular response. "In a multivariable regression including RVEF, NT-proBNP, the presence of atrial fibrillation, and GFR, only RVEF remained a significant predictor of CILP-1 levels." (PMID 38132152, 2023).
cardiomyopathy (1 paper, 2017). A disease of the heart muscle or myocardium proper. "Analysis of pathways that were dysregulated across cardiomyopathy phenotypes identified shared genes that were associated with extracellular matrix remodeling and thus likely fibrosis (THY1, CILP, OGN, THBS4, ASPN, HAPLN1,and SMOC2), as well as calcium (ADIPOQ, ASPN, THBS4, STAT4, and SMOC2)." (PMID 28098235, 2017).
gastric cancer (1 paper, 2017). A primary or metastatic malignant neoplasm involving the stomach. "For instance, allele frequency of CILP rs2073711 C is more common in Europeans than in Asians (The NCBI dbSNP database) and both alleles of certain polymorphisms have been associated with osteoporosis and gastric cancer among different racial groups." (PMID 29233086, 2017).
Hyperinsulinemia (1 paper, 2019). An increased concentration of insulin in the blood. "To address this question, we further performed EHCs to control blood glucose levels and investigated the impact of hyperinsulinemia alone on CILP-2 levels in healthy individuals." (PMID 30896018, 2019). "When fed with HFD, the suppression of HGP by hyperinsulinemia was 73% in Ad-GFP mice, but only ~48% in Ad-CILP-2 mice relative to NC-fed Ad-GFP mice (P < 0.05), indicating a marked decrease in hepatic insulin sensitivity." (PMID 30896018, 2019).
knee osteoarthritis (1 paper, 2019). "Measuring the change in the cartilage biomarker CILP-2 might be a valid and sensitive method to detect early development of knee osteoarthritis as CILP-2 appears to be related to cartilage thickness loss in certain individuals with increased risk of developing knee osteoarthritis." (PMID 31053993, 2019).
osteoblastic osteosarcoma (1 paper, 2024). A conventional osteosarcoma characterized by the predominance of osteoid matrix. "KAZALD1 is overexpressed in osteoblastic osteosarcoma and carcinoma-associated fibroblasts and CILP under expression is a known feature of the disease." (PMID 39701601, 2024).
osteophytes (1 paper, 2016). "NCOR2 and CD36 genes were associated with induction of radiographic knee OA measured as either a K/L grading of ≥2.0 or the presence of osteophytes, while the polymorphisms at CILP, TNA, IL1RN and variation at inflmmatory genes appeared to correlate with radiographic progression over time." (PMID 27457563, 2016).
rheumatoid arthritis (1 paper, 2023). A chronic, systemic autoimmune disorder characterized by inflammation in the synovial membranes and articular surfaces. "An immune response to CILP has also been suggested to contribute to the pathogenesis of inflammatory joint destruction present in rheumatoid arthritis (RA) and OA12." (PMID 38066013, 2023).
cancer (5 papers, 2018 to 2025). A tumor composed of atypical neoplastic, often pleomorphic cells that invade other tissues. "Namely, the expression levels of ATP1A2, CILP, and THSD4 were downregulated in cancer tissues compared with paracancerous tissues, whereas the expression levels of SMYD2 and GAPDHP1 were upregulated." (PMID 35498536, 2022). "In addition, quantitative real-time PCR results showed that the expression levels of ATP1A2, CILP, and THSD4 were downregulated and the expressions of SMYD2 and GAPDHP1 were upregulated in cancer tissues compared with normal tissues." (PMID 35498536, 2022). "However, the roles of AUNIP and CILP in this malignant tumor have not been fully studied." (PMID 41585903, 2025).
tumor (2 papers, 2018 to 2022). "In the TCGA cohort, CILP displayed a differential expression pattern based on different clinical factors, including age, clinical stage, tumor size, lymph node status, metastasis, estrogen receptor (ER) status, and progesterone receptor (PR) status." (PMID 35711946, 2022). "Regarding mechanism speculation, only the correlation between CILP and the tumor immune microenvironment was identified, but it fails to penetrate specific pathways or targets, which requires further study." (PMID 35711946, 2022).
CILP also shares sentences with these, for which no sentence is quoted: aortic stenosis (2 papers); cardiac diseases (2); musculoskeletal disorders (2); myocardial infarction (2); aortic valve stenosis (1); cervical cancer (1); diabetes mellitus (1); genetic disorder (1); hand osteoarthritis (1); hyperphosphatemia (1); hypertrophic cardiomyopathy (1); infarction (1); ischemic cardiomyopathy (1); joint diseases (1); keloid (1); laryngeal carcinoma (1); lipemia (1); melanoma (1); myopathy (1); Myxomatous mitral valve degeneration (1); oral cancer (1); osteoporosis (1); ovarian carcinoma (1); rheumatic diseases (1); thyroid tumours (1).